FTL (ferritin light chain)
Diseases named in the same sentence as FTL in open-access papers (continued):
Sharing a sentence is not in itself a finding about the gene and the disease.
liver cancer (4 papers, 2023 to 2025). An epithelial or non-epithelial malignant neoplasm that arises from the liver. "Knockdown of FTL significantly inhibited proliferation, migration, and invasive activity in liver cancer cells." (PMID 37354485, 2023). "FTH1, FTL were significantly overexpressed in the three liver cancer cell lines compared with normal liver cells." (PMID 37555866, 2023). "Notably, the downregulation of FTL resulted in a significant suppression of proliferation, migration, and invasive capabilities in liver cancer cells." (PMID 37354485, 2023). "We further detected 60 pairs of liver cancer tissues by immunohistochemistry, and found that the expression of FTH1, FTL in tumor tissues was significantly higher than that in para-tumor tissues." (PMID 37555866, 2023). "The varied expression levels of DEFRGs between the tumor and control groups in the TCGA-LIHC liver cancer dataset were compared, where ZFP36, NCOA4, FTH1, FTL, TNF, and PCBP1 were matched with the TCGA transcriptome data." (PMID 37555866, 2023). "Consistently, in the presence of cycloheximide (CHX, an inhibitor of protein translation), inhibition of USP8 promoted the degradation of endogenous FTL protein in human liver cancer cell line HepG2 and overexpression of USP8 delayed the protein turnover of exogenous FTL protein in HEK 293T cells." (PMID 37051673, 2023). "Finally, we validated the key prognostic genes FTH1, FTL, using qRT-PCR, and found that the expression of FTH1 and FTL was significantly higher in various liver cancer cells than in normal liver cells." (PMID 37555866, 2023).
acute myeloid leukemia (3 papers, 2023 to 2025). Acute myeloid leukemia (AML) is a group of neoplasms arising from precursor cells committed to the myeloid cell-line differentiation. "Increased expression of FTL and FTH genes encoding ferritin chains, as well as elevated serum ferritin concentrations, have prognostic significance in another hematologic malignancy, acute myeloid leukemia." (PMID 37895038, 2023). "In patients with breast cancer, for instance, increases in SF are strongly correlated with FTL rather than with FTH1, whereas these increases may be due to FTH1 overexpression in patients with acute myeloid leukemia (AML)." (PMID 39294443, 2024).
atherosclerosis (3 papers, 2009 to 2024). A disease characterized by the build-up of fatty material and calcium deposition in the arterial wall resulting in partial or complete occlusion of the arterial lumen. "Additionally, in vivo experiments showed that inhibiting ITCH reduced atherosclerosis progression and reversed ferroptosis in the aorta, with an associated increase in FTL protein expression in the aortas of mice." (PMID 39769287, 2024). "The treatment with DFO was demonstrated to attenuate atherosclerosis with a significant reduction in ferritin in the serum, iron, FTL and FTH mRNAs and proteins in the aortic tissues in ApoE–/– mice." (PMID 35669479, 2022). "The present results also appear to support a role for ferritin light chain (FTL) in atherosclerosis." (PMID 19750006, 2009). "Additionally, the in vivo experiments in this study demonstrated that inhibiting ITCH reduced the progression of atherosclerosis and reversed ferroptosis in the aorta, accompanied by increased FTL protein expression in the aortas of mice." (PMID 39769287, 2024). "The findings suggest that the beneficial effects of ITCH suppression on atherosclerosis are at least partially due to inhibiting the ITCH-FTL axis, with ITCH-mediated ubiquitination of FTL contributing to endothelial ferroptosis in atherosclerosis." (PMID 39769287, 2024).
cognitive defects (3 papers, 2017 to 2025). "A mutation in FTL resulted in neurodegenerative hereditary ferrinopathy, characterized by tremor and cognitive defects." (PMID 27188386, 2017).
leukemia (3 papers, 2021 to 2025). A malignant (clonal) hematologic disorder, involving hematopoietic stem cells and characterized by the presence of primitive or atypical myeloid or lymphoid cells in the bone marrow and the blood. "Our published TMT-labelled proteomics of primary leukemia samples compared to normal peripheral blood cells showed that the leukemic cells had increased iron-related proteins (FTH, FTL, TFRC, FECH, and TOM20)." (PMID 41188278, 2025).
pancreatic cancer (3 papers, 2021 to 2025). "To further confirm this finding, we generated PROGgeneV2 Kaplan–Meier survival curves by using data from The Cancer Genome Atlas (TCGA) and analyzed the association of the FTH1/FTL expression ratio with the overall survival of patients with pancreatic cancer." (PMID 39294443, 2024). "Hence, we also determined whether the FTH1 or FTL gene was correlated with a set of ferroptosis genes that were revealed to be highly associated with increased risks for pancreatic cancer." (PMID 34711879, 2021). "Ferritin, comprising heavy (FTH1) and light (FTL) chains, is the main iron storage protein, and pancreatic cancer patients exhibit elevated serum ferritin levels." (PMID 39294443, 2024). "We thus examined messenger (m)RNA expressions of FTH1 and FTL in pancreatic cancer patients using Oncomine datasets." (PMID 34711879, 2021). "The results also confirmed that high FTH1 expression is negatively correlated with the overall survival of patients with pancreatic cancer: patients with a higher FTH1/FTL expression ratio had significantly lower overall survival than did those with a lower FTH1/FTL expression ratio." (PMID 39294443, 2024). "Recent studies have suggested that FTH1 and FTL are associated with cancer risk and that this risk may vary with cancer type; therefore, we hypothesized that differential FTH1 and/or FTL expression in ferritin is involved in pancreatic cancer risk." (PMID 39294443, 2024). "mRNA expressions of neither FTH1 nor FTL were significantly associated with clinical stages of pancreatic cancer." (PMID 34711879, 2021). "The current results are consistent with the online database data: strong FTH1 but not FTL expression is significantly correlated with worsened survival of patients with pancreatic cancer as well as in those with high FTH1–KRAS co-occurrence." (PMID 39294443, 2024). "Furthermore, treatment with DFX substantially decreased FTH1 and FTL protein levels, indicating that DFX may exert its inhibitory effects on pancreatic cancer cell growth through the downregulation of FTH1 activation." (PMID 39294443, 2024). "However, FTL expression did not significantly differ among the pancreatic cancer cell lines." (PMID 39294443, 2024).
Stroke (3 papers, 2021 to 2025). Sudden impairment of blood flow to a part of the brain due to occlusion or rupture of an artery to the brain. "The data revealed that MGF significantly upregulated the expression of NRF2, GPX4, SLC7A11 and FTL, whereas ML385 inhibited the influence of MGF on these proteins, suggesting that MGF might inhibits ferroptosis in stroke by targeting the NRF2/ARE pathway." (PMID 40474971, 2025). "Six proteins (AGFG2, C1QTNF1, CHIT1, DNAJC15, FTL, and OLR1) have been reported to be implicated in other neurodegenerative diseases such as AD, ALS, or stroke, but not in PD." (PMID 37422510, 2023). "Although FTL was more expressed than AHSG, TTR, and FGG using gene expression data for normal human tissues, it remains debatable whether iron itself and iron accumulation were beneficial or harmful after experimental stroke." (PMID 34168538, 2021).
acute kidney injury (2 papers, 2024). Sudden and sustained deterioration of the kidney function characterized by decreased glomerular filtration rate, increased serum creatinine or oliguria. "FtL may facilitate immunomodulation and mitigate septic acute kidney injury (AKI)." (PMID 38957461, 2024).
Age-related cataract (2 papers, 2013 to 2022). A type of cataract (opacification of the lens) that forms during the course of aging. "At least 8 genes are known to be directly associated with age-related cataracts, including EPHA2, GJA8, GALT, SLC16A12, HSF4, GALK1, FTL, and CRYAA." (PMID 36107580, 2022). "Further studies will be required to determine the significance of FTL 5′-UTR and promoter variations located outside the IRE in the genetic etiology of age-related cataract." (PMID 23592921, 2013).
asthma (2 papers, 2022 to 2023). "On the contrary, the levels of FTL and FTL1 in lung tissues were decreased in asthma mice but increased after Ferr-1 and/or 3-MA treatment." (PMID 35154576, 2022). "Accordingly, FTL and FTH1, two main ferritins responsible for iron storage, were upregulated in BALF of asthma mice." (PMID 35154576, 2022). "In addition, we found that the expression of FTL and FTH1 was suppressed in the lung tissues of asthma model mice." (PMID 35154576, 2022).
colitis (2 papers, 2020 to 2023). Inflammation of the colon. "Nevertheless, similar to FTH, FTL expression in experimental colitis and its action to regulate ferroptosis are also controversial." (PMID 37153794, 2023). "In the present study, elevated FTL expressions were detected in the colon tissues of the colitis rats, which were downregulated after XJS treatment." (PMID 37153794, 2023). "The number of necrotic cell death, the MDA and iron contents and the FTL and FTH protein levels in colonic IECs were all decreased in the GSK 414-treated colitis mice." (PMID 32015337, 2020).
epilepsy (2 papers, 2022 to 2026). A brain disorder characterized by episodes of abnormally increased neuronal discharge resulting in transient episodes of sensory or motor neurological dysfunction, or psychic dysfunction. "We identify and validate ferroptosis-related genes (e.g., FTH1, FTL, PCBP1) as potential biomarkers and therapeutic targets, supported by congruent biochemical evidence of oxidative stress in this drug-resistant epilepsy." (PMID 42051157, 2026).
injury (2 papers, 2025 to 2026). Damage inflicted on the body as the direct or indirect result of an external force, with or without disruption of structural continuity. "In this study, we demonstrate that both FTH1 and FTL are significantly enriched in the serum, blood monocytes, and alveolar macrophages (AMs) of individuals with ARDS, a phenomenon we successfully replicate in a murine hyperoxia-induced acute lung injury (HALI) model." (PMID 41542049, 2026).
Obesity (2 papers, 2014 to 2016). Accumulation of substantial excess body fat. "We also detected 9 SNPs with P values from 8 × 10−4 to 9.7 × 10−18 near the gene FTL (ferritin light polypeptide), which is known to be strongly associated with human obesity and carriers of the risk allele reported to have increased appetite." (PMID 26968377, 2016). "SNPs (single nucleotide polymorphisms) on a chromosome 16 locus encompassing FTO, as well as IRX3, 5, 6, FTM and FTL are robustly associated with human obesity." (PMID 25242086, 2014).
osteosarcoma (2 papers, 2022 to 2023). A usually aggressive malignant bone-forming mesenchymal neoplasm, predominantly affecting adolescents and young adults. "A study on FTL and osteosarcoma showed that the expression of FTL in osteosarcoma cells was significantly lower than that in normal tissues in the transcriptome database." (PMID 36897430, 2023). "Besides COL1A2, the ferritin light chain (FTL) expression was shown in association with the response to chemotherapy and contributed to the proliferation, migration, and invasion of osteosarcoma cells." (PMID 36428591, 2022).
ovarian carcinoma (2 papers, 2023 to 2024). A malignant neoplasm originating from the surface ovarian epithelium. "Our results demonstrated higher levels of TRFC and FTH1/FTL proteins in ovarian cancer cells compared to immortalized ovarian epithelial cells." (PMID 38740757, 2024). "Lastly, most genes (FTL and FTH1) involved in the iron storage process displayed increased expression in ovarian cancer tissues, suggesting an association between this process and the initiation of ovarian cancer." (PMID 38186569, 2023). "We also observed strict iron regulation in ovarian cancer through FTH1 and FTL, protecting cells from platinum- or high iron-induced DNA damage." (PMID 38740757, 2024). "To reveal how ovarian cancer regulates iron homeostasis, we found that iron can induce the expression of FTH1/FTL." (PMID 38740757, 2024). "Our findings affirm the pro-cancer role of iron in ovarian cancer and reveal that iron advances platinum resistance by promoting DNA damage repair through FTH1/FTL/POLQ/RAD51 pathway." (PMID 38740757, 2024). "This suggests that platinum-induced DNA damage in ovarian cancer cells may trigger changes in cellular iron balance, potentially indicating an increased demand for iron and subsequent upregulation of FTH1 and FTL." (PMID 38740757, 2024).
preeclampsia (2 papers, 2019 to 2025). Preeclampsia is a hypertensive disorder of pregnancy that is characterized by new-onset hypertension with proteinuria presenting after 20 weeks of gestation, and depending on mild or severe forms may initially present with severe headache, visual disturbances, and hyperreflexia. "Reduced levels of FTL during pregnancy may initiate ferroptosis subsequently resulting in impaired remodelling of the uterine spiral arteries and ultimately leading to the development of preeclampsia." (PMID 39804099, 2025).
psoriasis (2 papers, 2022 to 2024). An autoimmune condition characterized by red, well-delineated plaques with silvery scales that are usually on the extensor surfaces and scalp. "Psoriasis skin-derived S.B cells expressed GPX4, FTL, and FTH1 at high levels, whereas control skin-derived S.G & S.S cells expressed high levels of GPX4, FTH1, NR4A1, NFE2L2, and MT1G." (PMID 35962439, 2022). "Similarly, the upregulation of PTGS2 and TFRC expression and decreased FTL, GPX4, and FTH1 mRNA levels were observed in psoriasis samples." (PMID 39308857, 2024). "In addition, some critical ferroptosis suppressor genes, such as GPX4, FTL, and FTH1, are expressed at high levels in the keratinocyte population in psoriasis." (PMID 35962439, 2022).
pulmonary TB (2 papers, 2022 to 2023). "Consistent with this notion, in the present study both FTH1 and FTL mRNA levels in peripheral blood mononuclear cells (PBMCs) were significantly higher in patients with pulmonary TB than in healthy controls and non-TB pneumonia patients." (PMID 37066876, 2023).
thyroid cancer (2 papers, 2012 to 2025). "Although there has been limited direct research on the specific role of FTL in thyroid disease, previous studies have suggested a potential link between ferritin levels and thyroid cancer." (PMID 39807704, 2025). "Thus, it is possible that ferritin, including FTL, may be involved in the pathogenesis or progression of thyroid cancer, but more researches are needed to clarify this relationship." (PMID 39807704, 2025). "In previous studies, we found that haptogloblin, ferritin light chain, and ferritin heavy chain were differentially expressed in the FNA of thyroid cancers." (PMID 22480342, 2012).
acute myocarditis (1 paper, 2021). The sudden onset of inflammation of heart muscle with myocellular necrosis; this is generally secondary to an infectious cause, and patients often have a recent history of a flu-like illness. "Both hCM and hCF treated with acute myocarditis patients’ sera exhibited an increase in FTL and FTH expression at the mRNA (all p < 0.05) but not at the intracellular protein level (data not shown)." (PMID 33917391, 2021).
anaplastic astrocytoma (1 paper, 2017). "Low levels of FTH-positive tumor cells and microglia/macrophages were associated with poor survival in anaplastic astrocytomas, while high amounts of FTL-positive microglia/macrophages had a negative prognostic value." (PMID 28837569, 2017). "Neither FTH nor FTL increased with malignancy grade, but low FTH expression by both tumor cells (p = 0.03) and microglia/macrophages (p = 0.01) correlated with shorter survival in patients anaplastic astrocytoma." (PMID 28837569, 2017).
Arthritis (1 paper, 2019). Inflammation of a joint. "However, the SDN map identified five cSABPs (ENO1, FTL, IMMT, PDCD6IP and HSPA6) that were associated with various types of arthritis." (PMID 31511554, 2019).
astrocytomas (1 paper, 2017). "The prognostic values of TfR1, FTH, and FTL in the individual astrocytoma grades were limited." (PMID 28837569, 2017). "Using whole slides of non-cultured patient tumor tissue, our results supported this showing that TfR1, FTH, and FTL were co-expressed to some extent with the stem cell marker CD133, and we furthermore found that TfR1 was elevated in GBMs and associated with short survival in astrocytomas." (PMID 28837569, 2017). "The aim of the present study was to investigate the expression and prognostic value of TfR1, FTL, and FTH in a patient cohort of 111 astrocytomas." (PMID 28837569, 2017). "However, high microglial/macrophage expression of FTL, but not FTH, correlated with shorter survival in all astrocytomas suggesting that development of future therapeutic strategies compromising iron flux should take tumors cells as well as microglia/macrophages into account." (PMID 28837569, 2017).
Ataxia (1 paper, 2022). Ataxia refers to impaired coordination of voluntary muscle movement. "Of note, one patient with an FTL mutation developed progressive ataxia from age 13 years and was ultimately diagnosed with neurodegeneration with brain iron accumulation 3 (OMIM 606159)." (PMID 35719373, 2022).
autoimmune thyroid disease (1 paper, 2023). Inflammatory disease of the thyroid gland due to autoimmune responses leading to lymphocytic infiltration of the gland. "Co-expressed genes of FTL were significantly associated with immune-associated signaling pathways, such as autoimmune thyroid disease, antigen processing and presentation, etc. via KEGG pathway analysis." (PMID 37441589, 2023).
Autoimmunity (1 paper, 2022). The occurrence of an immune reaction against the organism's own cells or tissues. "However, the FTL-like structure of microorganisms has a cross-immune reaction with human FTL, which activates human autoimmunity and causes pancytopenia." (PMID 35572557, 2022).
breast tumors (1 paper, 2020). "Moreover, authors of another study demonstrated that FTL was a marker of breast tumors with an aggressive phenotype." (PMID 32677981, 2020).
Cerebral ischemia (1 paper, 2025). Restriction of arterial blood supply to the brain associated with insufficient oxygenation to support the metabolic requirements of the tissue. "Western blot analysis revealed that cerebral ischemia marginally induced the expression of NRF2 and significantly decreased the expression of SLC7A11, GPX4, and FTL (P < 0.05 vs. sham)." (PMID 40474971, 2025).
cervical dystonia (1 paper, 2025). "Additionally, a known pathogenic variant in FTL (p.Glu58*) was identified in a patient with isolated adult‐onset cervical dystonia." (PMID 40533913, 2025).
chronic obstructive pulmonary disease (1 paper, 2024). A chronic and progressive lung disorder characterized by the loss of elasticity of the bronchial tree and the air sacs, destruction of the air sacs wall, thickening of the bronchial wall, and mucous accumulation in the bronchial tree. "Elevated FTL expression levels are linked to irritations caused by cigarette smoke and the onset of chronic obstructive pulmonary disease (COPD)." (PMID 38672772, 2024).